PLK4 (polo like kinase 4)
Diseases named in the same sentence as PLK4 in open-access papers (continued):
Sharing a sentence is not in itself a finding about the gene and the disease.
cancer (continued). "However, there still are challenges for the strategy for targeting Plk4, because currently the etiology of Plk4 in tumorigenesis and cancer development has not been fully understood." (PMID 33777739, 2021). "Since ALKBH4 knockdown downregulated the expression of PLK1 and PLK4, ALKBH4 may function as a tumour promoter by accelerating cancer cell proliferation via upregulation of E2F1 signalling in early stage, and by promoting metastasis via upregulation of PLK signalling in late-stage NSCLC." (PMID 33883577, 2021). "Therefore, PLK4 activity is likely required for CA, but genomic alterations in the core centriole duplication machinery, including PLK4, are not likely the primary drivers of CA in human cancer." (PMID 32681070, 2020). "Additionally, we examined whether concurrent overexpression of POLQ and PLK4, which was detected in LAC, is also observed in various other human cancers using the data of 17 cancer types from the TCGA database." (PMID 31137743, 2019). "Therefore, it may be possible to inhibit PLK4 in cancers with or without PLK4 overexpression to reverse CA, and tools to inhibit PLK4 have already been developed." (PMID 31506331, 2019). "Inhibition of PLK4 by centrinone dephosphorylates and translocates TFEB and TFE3 to the nucleus and supports cancer proliferation in the absence of centrosome, implying there are impediments to adopting centrosome depletion alone as a treatment strategy." (PMID 41488365, 2025). "In the cancer cell lines studied here, the inhibitory effect of FAM46C on Plk4 activity was not dependent on its poly(A) RNA polymerase function." (PMID 32807875, 2020). "We show that while exosome-induced cancer cell motility requires neither centrosomes nor the MT network, it is critically dependent on CEP192, the CEP192 interacting kinase PLK4, and the Chromosomal Passenger Complex (CPC) protein Aurora Kinase B (AURKB)." (PMID 31142743, 2019). "Together, these results strongly suggest that there exists a negative correlation between Plk4 and KLF14 expressions in human cancers." (PMID 26439168, 2015). "Our studies suggest that targeting contextual non-directional cell motility through dual inhibition of PLK4 and AURKB might be an important therapeutic goal in the cancer clinic." (PMID 31142743, 2019). "However, our results showed that centrinone, the most selective inhibitor for PLK4, did not induce polyploidy of the cancer cells, which raises the hypothesis that the major factor responsible for polyploidy is inhibition of AURKB rather than PLK4." (PMID 31035676, 2019).
tumor (76 papers, 2009 to 2026). "Recent studies leveraging in vitro and in vivo models have shed light on the role of PLK4-mediated centrosome amplification, a frequent cause of aneuploidy, in skin biology and skin carcinogenesis." (PMID 40940791, 2025). "PLK4 is highly expressed in glioma where its higher expression associates with poorer prognosis and regulation of the tumor immune microenvironment, such as reduced infiltration of macrophages." (PMID 41092110, 2025). "Taken together, these results indicate that tumor PLK4 protein expression is negatively linked with survival in EC patients who underwent surgical resection." (PMID 38326803, 2024). "A new study indicated that higher PLK4 protein expression was negatively associated with tumor characteristics and shortened survival in EC patients, suggesting the promoting effect of PLK4 on EC progression." (PMID 39349439, 2024). "A tumor PLK4 IHC score > 6 or > 3 associates with shortened DFS and OS in EC patients who undergo surgical resection." (PMID 38326803, 2024). "This study revealed that tumor PLK4 protein expression was positively associated with lymphovascular invasion and FIGO stage in EC patients who underwent surgical resection." (PMID 38326803, 2024). "Tumor PLK4 protein expression positively associated with lymphovascular invasion (P = 0.008) and Federation of Gynecology and Obstetrics (FIGO) stage (P = 0.005)." (PMID 38326803, 2024). "Through this occurrence, we confirmed that a higher PLK4 expression was associated with a poor tumor prognosis and a high proportion of primary tumors." (PMID 37760631, 2023). "With respect to the correlation between PLKs and clinical features in NSCLC patients, it has been demonstrated that increased PLK4 is linked with greater tumor size and LYN metastasis in NSCLC patients." (PMID 36684318, 2022). "We then obtained the top 100 genes positively associated with PLK4 expression using the GEPIA2 tool combined with all TCGA tumor expression data." (PMID 36620611, 2022). "Several independent prognostic factors were incorporated into the nomograms, namely tumor grade, expression levels of PLK4, IDH mutation status, 1p/19q codeletion status, and the MGMT promoter status." (PMID 36620611, 2022). "Further investigations are needed to reveal the role and mechanism of Plk4 in tumor-associated inflammation." (PMID 33777739, 2021). "Tumours caused by chronic PLK4 activation show different karyotypes and high heterogeneity of the tissue, which indicates that tumours undergo continuous errors in chromosome segregation." (PMID 32485126, 2020). "Summarized, whereas PLK2 and PLK3 are considered to be tumor suppressors, PLK1 and PLK4 are associated with carcinogenesis and are often overexpressed in tumor cells." (PMID 33053667, 2020). "These mice show accelerated tumour formation, behavioural defects and cell hyperproliferation associated with elevated Plk4 expression in several tissues including the pancreas and skin." (PMID 26701933, 2015).
tumor (continued). "Plk4 is known to regulate centriole biogenesis, and its deregulation has been linked to tumor development." (PMID 22768216, 2012). "High PLK4 expression might also be implicated in the suppression of the immune tumor microenvironment." (PMID 41092110, 2025). "PLK4 was overexpressed in tumor tissues and was linked with poor disease-free survival." (PMID 41488365, 2025). "Hence, this study explored the distribution of tumor PLK4 protein expression in EC patients who underwent surgical resection as well as its association with tumor characteristics and survival using multiple cutoff values." (PMID 38326803, 2024). "Therefore, increased tumor PLK4 protein expression is linked with elevated FIGO stage in EC patients who underwent surgical resection." (PMID 38326803, 2024). "Furthermore, PLK4 was closely associated with the degree of tumor differentiation and lymph node metastasis in human CRC tissues." (PMID 35912011, 2022). "A higher level of Plk4 has been found in NB both primary and metastatic and is associated with a poor prognosis, which suggested that Plk4 could be a potential tumor-promoting factor of NB." (PMID 33777739, 2021). "PLK4 deficiency led to enhanced doxorubicin-mediated anti-tumor effects." (PMID 34162828, 2021). "These inhibitors may be used, as we showedhere, as monotherapy, in combination with standard anthracycline therapy or with other drugs, suchas a recently identified PLK4 inhibitor, which show strong anti-tumor activity againstPten-deficient BC." (PMID 25330770, 2014). "Decreased expression of PLK4 in HCC was associated with larger tumor size, indicating that the loss of PLK4 may facilitate HCC growth." (PMID 22829937, 2012). "Dysregulation of PLK4 caused disturbance of centrosome duplication, which may ultimately resulted in occurrence of tumor." (PMID 22829937, 2012). "Using structural biology‐guided approaches, Vallée and colleagues systematically validated the synthetic lethal effect of the PLK4 inhibitor RP‐1664 in TRIM37‐amplified tumours." (PMID 41537447, 2026). "In a professional context, combining PLK4 inhibitors with chemotherapeutic agents such as sorafenib has been shown to result in a synergistic anti-tumour effect in vitro." (PMID 40710347, 2025). "The impact of CFI-400945 on tumor growth in vivo was validated using PLK4-mutant patient-derived xenograft models." (PMID 40860200, 2025). "The mouse tumor xenograft model was established subcutaneously implanting with either PLK4 knockdown or the control SK-N-AS cells into the groins each nude mouse." (PMID 40860200, 2025). "Pharmacological inhibition of PLK4 reduces cell proliferation in vitro and suppresses tumor growth in vivo, supporting its therapeutic relevance." (PMID 40860200, 2025). "Another study found that PLK4 overexpression in NB tissues was negatively correlated with miR-338-3p, a tumor suppressor." (PMID 41488365, 2025). "Same as our previous results, both tumor volume and weight were notably reduced in the PLK4-knockdown group compared with the control group." (PMID 40860200, 2025). "A bioinformatic-based study of neonatal dermal fibroblasts revealed differential expression of PLK4 depending on recovery time following UV exposure, supporting its involvement in skin carcinogenesis." (PMID 40940791, 2025). "The selective PLK4 inhibitor CFI-400945 exhibits dual anti-tumor activity by promoting terminal differentiation and suppressing proliferation." (PMID 40860200, 2025).
tumor (continued). "PLK4 expression in the tumor tissues markedly varied with the degree of differentiation, and it was notably elevated in poor-differentiated regions compared with well-differentiated regions, wherein the expression of PHOX2B, CXCR4, and cyclin D1 was higher." (PMID 40860200, 2025). "It was suggested that the ATAD2-dependent transcriptional regulation of PLK4 was essential for tumor growth and treatment resistance in GBM cells." (PMID 41488365, 2025). "Doses that induced anti-tumor activity elevated both PLK4 and p21 protein levels in a dose- and time-dependent manner, confirming target modulation by RP-1664 at biologically active exposures." (PMID 40766251, 2025). "In summary, tumor PLK4 protein expression reflects lymphovascular invasion (P = 0.008) and higher FIGO stage (P = 0.005) in EC patients who undergo surgical resection." (PMID 38326803, 2024). "DFS was shortened in patients with a tumor PLK4 IHC score > 3 compared to those with a tumor PLK4 IHC score ≤ 3 (P = 0.009)." (PMID 38326803, 2024). "The mean tumor PLK4 IHC score was 3.8 ± 3.3, ranging from 0 to 12, in EC patients who underwent surgical resection." (PMID 38326803, 2024). "In particular, CSF1 and/or PLK4 inhibition can increase the number of tumor-infiltrating M1 macrophages in GBM63,64, thereby reversing immunosuppression." (PMID 39054369, 2024). "Tumor PLK4 protein expression reflects lymphovascular invasion and higher FIGO stage in EC patients who receive surgical resection." (PMID 38326803, 2024). "There were 26.1% patients with a tumor PLK4 IHC score = 0, 24.6% patients with a score of 1–3, 27.5% patients with a score of 4–6, and 21.8% patients with a score of 7–12." (PMID 38326803, 2024). "Tumor tissue samples were obtained for tumor PLK4 protein expression detection via immunohistochemistry (IHC)." (PMID 38326803, 2024). "If additional perturbations need to be applied, such as PLK4 overexpression for selective PIDDosome activation, to unravel tumor-suppressive functions for these BH3-only proteins in this disease model, remains to be explored." (PMID 38552015, 2024). "Tumor PLK4 protein expression was increased in patients with higher FIGO stage than those with lower stage (P = 0.005)." (PMID 38326803, 2024). "Their authors also suggest correlations between the expression of PLK4, tumor stage, and poor prognosis for patients." (PMID 39329988, 2024). "PLK4 is reported to serve as a marker for tumor features and poor outcomes in gynecologic malignancy." (PMID 38326803, 2024). "Patients with a tumor PLK4 IHC score > 6 had worse DFS than those with a tumor PLK4 IHC score ≤ 6 (P < 0.001)." (PMID 38326803, 2024). "For example, previous studies have shown that in the intestine, APCmin mutant mice that experience centrosome amplification show accelerated tumor onset, while in the skin, chemical carcinogenesis was unaffected by PLK4 overexpression." (PMID 38552015, 2024). "After adjustment, a tumor PLK4 IHC score > 6 (vs. ≤ 6) (hazard ratio (HR): 3.156, P = 0.008) or > 3 (vs. ≤ 3) (HR: 3.918, P = 0.026) was independently associated with shortened DFS and OS." (PMID 38326803, 2024). "In summary, the CRC cell biological characteristics changed by PLK4 expression strongly suggest a tumor promoting function for PLK4 in CRC progression." (PMID 37324947, 2023). "Consistently, both the qRT-PCR analysis and WB analysis of the 15 paired CRC and adjacent non-tumor tissue specimens indicated that 14 out of the 15 pairs of samples had higher levels of PLK4 expression in the tumor tissues." (PMID 37324947, 2023).
tumor (continued). "Together, these findings demonstrated that knockdown PLK4 in CRC cells inhibited tumor growth and metastasis in xenograft models, further revealing a critical role for PLK4-induced autophagy in the initiation of tumor dormancy." (PMID 37324947, 2023). "Collectively, these data implied that PLK4 downregulation induced autophagy was sufficient to maintain tumor cell dormancy." (PMID 37324947, 2023). "To evaluate the role of PLK4 in LUAD, we compared the PLK4 expression between tumor and normal samples." (PMID 37760631, 2023). "PLK4 expression is a critical factor for evaluating tumor proliferation, thus we intended to explore the relationship between PLK4 expression and CRC dormancy." (PMID 37324947, 2023). "Mechanistically, downregulation of PLK4 induced autophagy contributed to restoring phenotypically aggressive tumor cells to a dormant state through the MAPK signaling pathway, and inhibition of autophagy would trigger apoptosis of dormant cells." (PMID 37324947, 2023). "Our findings reveal that downregulation of PLK4-induced autophagy contributes to tumor dormancy and autophagy inhibition leads to apoptosis of CRC dormant cells." (PMID 37324947, 2023). "This signified that the percentage of apoptotic dormant tumor cells increased significantly following autophagy inhibition and PLK4 downregulation induced autophagy regulated cell dormancy mainly through the p38 MAPK signaling pathway." (PMID 37324947, 2023). "Because of the complexity of the tumor microenvironment, the exact molecular mechanism of how Plk4 contributes to tumorigenesis, and its effect in stem-cell features, is still poorly understood." (PMID 36797240, 2023). "The samples used for survival analysis included 514 primary tumor samples with PLK4 gene expression and clinical data and 505 samples with survival data." (PMID 37760631, 2023). "The DNA methylation level of PLK4 was significantly lower in ccRCC tumor tissues compared to paracancerous samples." (PMID 36176741, 2022). "We then integrated data from normal tissues obtained from the GTEx database to further compare differences in PLK4 mRNA expression levels between normal tissues and tumor tissues." (PMID 36620611, 2022). "Although PLK4 was shown to be aberrantly expressed in many tumor types in the recently published literature, it is also expressed at low levels in proliferative tissues, such as the pancreas and skin." (PMID 35670224, 2022). "As a result of high PLK4 expression, immune and stromal cells were less likely to infiltrate into several tumors, resulting in a higher tumor purity." (PMID 36620611, 2022). "Next, we applied the HPA approach to analyze PLK4 protein levels in normal and tumor tissues separately." (PMID 36620611, 2022). "The CFI-400945 (PLK4 inhibitor) was administered to mice bearing intracranial murine tumor, and the efficacy was significantly proved by living imaging and HE staining." (PMID 36620611, 2022). "Obviously, PLK4 plays an important and tumor heterogeneous role in tumorigenesis and development, while its expression and role in ccRCC have not been revealed." (PMID 36176741, 2022). "Next, the correlation of the PLK4 expression in ccRCC with immune cells and immunosuppressive cytokines that make up the immune microenvironment of the tumor was analyzed." (PMID 36176741, 2022). "Correlations between PLK4 and tumor-infiltrating immune cells and cytokines exerting immunosuppression were analyzed using the TIMER database and the TISIDB databases." (PMID 36176741, 2022). "To understand the impact of PLK4 in aberrant tumor proliferation, we investigated and analyzed PLK4 coexpression genes to predict the role of PLK4 in aberrant tumor cell proliferation." (PMID 36176741, 2022).